SPATA2 (spermatogenesis associated 2)
Description:
Bridging factor that mediates the recruitment of CYLD to the LUBAC complex, thereby regulating TNF-induced necroptosis. Acts as a direct binding intermediate that bridges RNF31/HOIP, the catalytic subunit of the LUBAC complex, and the deubiquitinase (CYLD), thereby recruiting CYLD to the TNF-R1 signaling complex (TNF-RSC). Required to activate the 'Met-1'- (linear) and 'Lys-63'-linked deubiquitinase activities of CYLD. Controls the kinase activity of RIPK1 and TNF-induced necroptosis by promoting 'Met-1'-linked deubiquitination of RIPK1 by CYLD (By similarity).
Synonyms: KIAA0757; PD1; tamo; PPP1R145
Tractability: PROTAC: ubiquitination databases record sites on it; its protein half-life has been measured.
Gene: Protein-coding gene on chromosome 20 (49,903,391 to 49,915,550, reverse strand). Ensembl gene ENSG00000158480.
Subcellular location: Cytoplasm; Nucleus
Subcellular location (Human Protein Atlas): Nucleoli fibrillar center; Nucleoplasm
Pathways (Reactome):
Signal Transduction: Regulation of TNFR1 signaling; TNFR1-induced NF-kappa-B signaling pathway; TNFR1-induced proapoptotic signaling
Gene Ontology:
Molecular function: protein binding; protein-containing complex binding; signaling receptor complex adaptor activity; ubiquitin-specific protease binding
Biological process: protein K63-linked deubiquitination; protein linear deubiquitination; regulation of inflammatory response; regulation of necroptotic process; regulation of tumor necrosis factor-mediated signaling pathway; spermatogenesis
Cellular component: cytoplasm; cytosol; nucleus
Genetic constraint (gnomAD): Loss-of-function variants: 8 observed, 35.81 expected, observed/expected ratio (o/e) 0.22, 90% interval 0.13 to 0.4. The upper end of that interval is the gene's LOEUF score, 0.4, which puts it in group 1 of 6, group 1 being the genes least tolerant of losing a copy. Missense variants: 650 observed, 715.54 expected, observed/expected ratio (o/e) 0.91, 90% interval 0.85 to 0.97. Synonymous variants: 293 observed, 309.28 expected, observed/expected ratio (o/e) 0.95, 90% interval 0.86 to 1.04.
Homologues: Orthologues: chimpanzee SPATA2 (99% identical), macaque SPATA2 (98% identical), dog SPATA2 (90% identical), pig SPATA2 (90% identical), rat Spata2 (86% identical), mouse Spata2 (85% identical), guinea pig SPATA2 (84% identical), rabbit SPATA2 (79% identical), tropical clawed frog spata2 (61% identical), zebrafish spata2 (41% identical), Drosophila melanogaster tamo (18% identical). Paralogues in human: SPATA2L (15% identical).
Diseases named in the same sentence as SPATA2 in open-access papers:
SPATA2 is named in the same sentence as 18 diseases in open-access papers, as found by Europe PMC text mining. Sharing a sentence is not in itself a finding about the gene and the disease. The quoted sentences say what the papers report.
ovarian carcinoma (2 papers, 2020 to 2022). A malignant neoplasm originating from the surface ovarian epithelium. "TNF-α and IL-1β induced SPATA2 expression in ovarian cancer cells and that increased SPATA2 expression was associated with poor prognosis of ovarian cancer patients." (PMID 35754839, 2022). "In addition, the spermatogenesis-associated protein 2 (SPATA2) has been shown to be a novel predictor of the outcome in ovarian cancer." (PMID 32373210, 2020).
psoriasis (2 papers, 2022 to 2025). An autoimmune condition characterized by red, well-delineated plaques with silvery scales that are usually on the extensor surfaces and scalp. "Another member of the spermatogenesis-related protein family, SPATA2, is associated with the autoimmune disorder of psoriasis." (PMID 35965557, 2022). "Concerning miRNAs, it has been identified that hsa-miR-19a-3p has great potential to become a biomarker for psoriasis because it binds to the mRNA of seven genes (CAST, TSC1, SPATA2, ERAP1, TNIP1, ERBB3 and SDC4) thatare associated with psoriasis." (PMID 40725409, 2025).
brain inflammation (1 paper, 2023). "The knockdown of SPATA2 leads to the activation of P38MAPK and NLRP3 inflammasome and the enhancement of NF-κB signaling, indicating that SPATA2 plays a protective role against brain inflammation induced by ischemia/reperfusion injury." (PMID 37528851, 2023).
cervical cancer (1 paper, 2022). A primary or metastatic malignant neoplasm involving the cervix. "According to research, increased SPATA2 expression is related to a poor prognosis in various cancers, such as ovarian or cervical cancer." (PMID 36186479, 2022).
lymph node metastasis (1 paper, 2022). "The expression of SPATA2 was higher in patients without lymph node metastasis (p < 0.001)." (PMID 36186479, 2022).
Obesity (1 paper, 2022). Accumulation of substantial excess body fat. "Comparing the body weight of AAV-injected Sim1-cre mice versus AAV-injected wild-type littermates, we found that overexpression of Snca and Igsf8 caused an exacerbation of HFD-induced obesity, whereas overexpression of Spata2, Pole4, Fndc4, Smim12, or Arrb1 had no impact on body weight." (PMID 36175420, 2022).
Stroke (1 paper, 2023). Sudden impairment of blood flow to a part of the brain due to occlusion or rupture of an artery to the brain. "After combining the mRNAs screened out via the LASSO, SVM, and RF algorithms, three diagnostic mRNAs (SPATA2, ZNF208, and YTHDC1) were identified for post-stroke depression." (PMID 37528851, 2023).
tumor (8 papers, 2022 to 2025). "Although closely linked to the expression of TNF in the tumor context, these data suggest a role of SPATA2 in tumorigenesis which will necessarily have to be confirmed by further investigations into other neoplasms." (PMID 36402749, 2022). "SPATA2 and CYLD deficiency significantly reduced tumor growth in BALB/c mice but not in Rag2-/- BALB/c mice, suggesting that adaptive immune cells were required for tumor regression." (PMID 36531014, 2022). "We found high SPATA2 expression in tumor tissues from patients with a relatively poor prognosis." (PMID 36186479, 2022). "We therefore hypothesized that increased T-cell chemokine expression upon ablation of SPATA2 or CYLD is driven by elevated IFN-γ-STAT1 signaling in tumor cells." (PMID 36531014, 2022). "To determine whether CYLD exerts a similar effect on tumor-intrinsic chemokine production as SPATA2, we transiently knocked down CYLD by RNAi and measured CXCL9, CXCL10, and CXCL11 secretion." (PMID 36531014, 2022). "Finally, we demonstrated that tumor-specific deletion of SPATA2 and CYLD enhances anti-PD-1 response in vivo." (PMID 36531014, 2022). "Furthermore, SPATA2’s spatial trajectory analysis revealed that among all examined cell types (including SPP1_Macro, MYH11_myoCAF and MCs), VCAN_eCAF was the only population that exhibited concordant spatial variation with tumor fibrosis scores in terms of cellular abundance." (PMID 41258075, 2025). "We identified SPATA2 and its interacting partner, CYLD, as tumor-intrinsic regulators of T cell chemokines, including CXCL10, via a novel mechanism." (PMID 36531014, 2022). "We therefore surmised that SPATA2 and CYLD suppress the production of T-cell chemokines from tumor cells, in part by regulating STAT1 protein levels and restraining STAT1 signaling (but not NF-κB signaling) emanating from IFN-γ stimulation." (PMID 36531014, 2022). "In summary, we identified SPATA2 and CYLD as novel regulators of T/NK cell-attracting chemokines CXCL9, CXCL10, CXCL11 in tumor cells." (PMID 36531014, 2022). "GEGFR, CD40, SPATA2, ZBP1, ID1, and MYC showed a significant CNV amplification in most tumour types; however, TLR3, PDHB, FAS, and MAP3K showed a significant CNV deletion in most tumour types." (PMID 36186436, 2022). "Here we showed a redundant role of SPATA2 and CYLD in the regulation of STAT1 activation and IFN-γ-induced genes in tumor cells." (PMID 36531014, 2022). "In contrast, tumor samples had lower levels of IPMK (p = 0.0010), SPATA2 (p = 0.0071), and KLF9 (p = 0.0002)." (PMID 36186479, 2022). "Genetic ablation of SPATA2 or CYLD in murine CRC tumors increased CXCL10 expression and T cell accumulation in the TME, concomitant with retarded tumor growth." (PMID 36531014, 2022). "In a subsequent study, the same authors analyzed the tumor expression of TNF and its regulator SPATA2 in relation to the clinical-pathological characteristics and clinical outcome of patients with endometrial carcinoma (EC)." (PMID 36402749, 2022). "By specifically deleting SPATA2 and CYLD in human and mouse CRC cell lines, we showed that these two proteins inhibit STAT1 accumulation and activation and subsequently CXCL10 expression in tumor cells." (PMID 36531014, 2022). "Finally, we assessed if ablation of SPATA2 and CYLD can ameliorate immune exclusion in CRC tumors by evaluating tumor growth and intratumoral immune infiltration in BALB/c mice implanted with Spata2-KO, Cyld-KO, or WT CT26 cells." (PMID 36531014, 2022). "The collective evidence therefore suggest that SPATA2 over-expression is associated with a non-T-cell-inflamed TME in CRC, and that SPATA2 might mediate T cell exclusion by inhibiting the production of CXCL9, CXCL10, and CXCL11 from tumor cells." (PMID 36531014, 2022). "Moreover, SPATA2 and CYLD deficiency did not significantly impact tumor-intrinsic fitness, as evidenced by comparable cell proliferation kinetics in vitro between KO and WT cells." (PMID 36531014, 2022).
tumor (continued). "Therefore, we hypothesized that SPATA2 and CYLD are suppressing chemokine production in tumor cells by modulating NF-κB and/or STAT1 signaling." (PMID 36531014, 2022).
cancer (4 papers, 2022). A tumor composed of atypical neoplastic, often pleomorphic cells that invade other tissues. "This increased SPATA2 expression in some types of cancers could be explained by the presence in its promoter region of several binding sites for transcription factors such as NF1 which plays an important role in the regulation of cell growth and in tumorigenesis." (PMID 36402749, 2022). "Of these DEGs, 6 (EGFR, GATA3, DIABLO, CFLAR, RIPK3, and MAPK8) were repressed, while (ZBP1, PLK1, SPATA2, BCL2, ALK, FASLG, TNFRSF21, and LEF1) were upregulated in cancer cases." (PMID 35610275, 2022).
infection (1 paper, 2016). The state of being infected such as from the introduction of a foreign agent such as serum, vaccine, antigenic substance or organism. "This adds SPATA2 to the still growing list of regulatory components of LUBAC and identifies a new modulator of important pathways involved in inflammation and infection." (PMID 27591049, 2016).
SPATA2 also shares sentences with these, for which no sentence is quoted: pancreatic cancer (2 papers); autoimmune disorder (1); Cerebral ischemia (1); clear cell ovarian cancer (1); colorectal cancer (1); Infertility (1); non-small cell lung carcinoma (1); serous ovarian cancer (1).